TCTN1 (tectonic family member 1)
Description:
Component of the tectonic-like complex, a complex localized at the transition zone of primary cilia and acting as a barrier that prevents diffusion of transmembrane proteins between the cilia and plasma membranes. Regulator of Hedgehog (Hh), required for both activation and inhibition of the Hh pathway in the patterning of the neural tube. During neural tube development, it is required for formation of the most ventral cell types and for full Hh pathway activation. Functions in Hh signal transduction to fully activate the pathway in the presence of high Hh levels and to repress the pathway in the absence of Hh signals. Modulates Hh signal transduction downstream of SMO and RAB23 (By similarity).
Synonyms: TECT1; FLJ21127; JBTS13
Tractability: Antibody: UniProt places it where antibodies can reach, with high confidence; UniProt predicts a signal peptide or a membrane-spanning region; its Gene Ontology location is reachable by antibodies, with medium confidence. PROTAC: ubiquitination databases record sites on it.
Gene: Protein-coding gene on chromosome 12 (110,614,027 to 110,663,431, forward strand). Ensembl gene ENSG00000204852.
Subcellular location: Cytoplasm, cytoskeleton, cilium basal body; Secreted
Subcellular location (Human Protein Atlas): Actin filaments; Primary cilium; Nucleoplasm
Pathways (Reactome):
Organelle biogenesis and maintenance: Anchoring of the basal body to the plasma membrane
Gene Ontology:
Biological process: cilium assembly; protein localization to ciliary transition zone
Cellular component: ciliary transition zone; cytosol; MKS complex; extracellular region; membrane
Genetic constraint (gnomAD): Loss-of-function variants: 56 observed, 61.74 expected, observed/expected ratio (o/e) 0.91, 90% interval 0.73 to 1.13. The upper end of that interval is the gene's LOEUF score, 1.13, which puts it in group 4 of 6, group 1 being the genes least tolerant of losing a copy. Missense variants: 640 observed, 716.23 expected, observed/expected ratio (o/e) 0.89, 90% interval 0.84 to 0.95. Synonymous variants: 267 observed, 286.52 expected, observed/expected ratio (o/e) 0.93, 90% interval 0.84 to 1.03.
Homologues: Orthologues: chimpanzee TCTN1 (98% identical), macaque TCTN1 (93% identical), dog TCTN1 (79% identical), pig TCTN1 (77% identical), guinea pig TCTN1 (74% identical), mouse Tctn1 (70% identical), rat Tctn1 (70% identical), rabbit TCTN1 (62% identical), tropical clawed frog tctn1 (44% identical), zebrafish tctn1 (31% identical), Caenorhabditis elegans tctn-1 (14% identical). Paralogues in human: TCTN3 (27% identical), TCTN2 (20% identical).
Diseases named in the same sentence as TCTN1 in open-access papers:
TCTN1 is named in the same sentence as 21 diseases in open-access papers, as found by Europe PMC text mining. Sharing a sentence is not in itself a finding about the gene and the disease. The quoted sentences say what the papers report.
ciliopathy (8 papers, 2012 to 2023). A genetic disorder of the cellular cilia or the cilia anchoring structures, the basal bodies, or of ciliary function. "We previously found that Tctn1 is an essential component of the transition zone required for cilium-dependent Hh signaling in mice, and that human TCTN1 is mutated in another ciliopathy, Joubert syndrome." (PMID 26540106, 2015). "To test this hypothesis, we generated animals with intra- and inter-complex double mutations, with an emphasis on the ciliopathy gene Tectonic1 (Tctn1 [MIM 609863])." (PMID 26540106, 2015). "In addition, a recent study showed that TCTN1 was part of a ciliopathy-associated protein complex and interacted with several other proteins associated with ciliopathies." (PMID 25304031, 2014). "TCTN1 is also a known protein component of a ciliopathy-associated protein complex and could interact with Mks1, Tmem216, Tmem217, and several other proteins that are associated with ciliopathies to modulate ciliary assembly and trafficking." (PMID 31297133, 2019). "Recessive mutations in TCTN1 cause Joubert syndrome (JBTS, MIM #614173), a ciliopathy characterized by cerebellar and brainstem malformations." (PMID 30950222, 2019). "Thus Tctn1-/-Bbs1-/- double mutants have abrogated Hh pathway activation, likely resulting in the exacerbation of ciliopathy phenotypes compared to either Tctn1 or Bbs1 single mutants." (PMID 26540106, 2015).
esophageal squamous cell carcinoma (6 papers, 2019 to 2023). Esophageal squamous cell carcinoma (ESCC) is a type of esophageal carcinoma (EC) that can affect any part of the esophagus, but is usually located in the upper or middle third. "MiR-216a-5p repressed esophageal squamous cell carcinoma (ESCC) cell proliferation while promoted apoptosis via TCTN1 targeting." (PMID 36740668, 2023). "The regulatory effect of miR-216a has also been identified in esophageal squamous cell carcinoma by targeting TCTN1 to inhibit cell proliferation and induce apoptosis." (PMID 33842327, 2021). "For example, targeting TCTN1 with miR-216a-5p could inhibit the proliferation of esophageal squamous cell carcinoma cells and induce apoptosis." (PMID 37819496, 2023).
glioblastoma (3 papers, 2014 to 2022). The most malignant astrocytic tumor (WHO grade IV). "ARF deletion leads to increased expression of tectonic family member 1 (TCTN1) protein that results in increased promotion of glioblastoma." (PMID 36185622, 2022). "Moreover, in human glioblastoma (GBM) TCTN1 overexpression predicts poor clinical outcome for patients." (PMID 29221125, 2017).
Joubert syndrome (3 papers, 2015 to 2021). Joubert syndrome (JS) is characterized by congenital malformation of the brainstem and agenesis or hypoplasia of the cerebellar vermis leading to an abnormal respiratory pattern, nystagmus, hypotonia, ataxia, and delay in achieving motor milestones. "Several PSGs are associated with Joubert syndrome, including AHI1, CSPP1, and TCTN1, and are essential for cerebellar development." (PMID 33441416, 2021).
gastric cancer (2 papers, 2019 to 2024). A primary or metastatic malignant neoplasm involving the stomach. "Early reports indicated that TCTN1 was associated with numerous tumors including gastric cancer, human thyroid cancer, as well as ESCC." (PMID 38514579, 2024). "Recent studies revealed that TCTN1 is widely up-regulated in various types of human cancer, including gastric cancer, colorectal cancer, prostate cancer, and glioblastoma and acts as an oncogene via promoting proliferation, migration, or inhibiting apoptosis." (PMID 31297133, 2019). "Silencing of TCTN1 by lentivirus-mediated RNA interference in gastric cancer and pancreatic cancer cells and reduction of proliferation were observed, suggesting that the knockdown of TCTN1 is sufficient to inhibit cell viability." (PMID 31297133, 2019).
holoprosencephaly (2 papers, 2018 to 2023). Holoprosencephaly (HPE) is a complex brain malformation resulting from incomplete cleavage of the prosencephalon, occurring between the 18th and 28th day of gestation, and affecting both the forebrain and face, which results in neurological manifestations and facial anomalies of variable severity. "Tctn1 null mice present with heterotaxia, holoprosencephaly, microphthalmia, and hind limb polydactyly, similar to the phenotypes of mice with Shh signaling defects." (PMID 29725084, 2018).
melanoma (2 papers, 2025). A malignant, usually aggressive tumor composed of atypical, neoplastic melanocytes. "In clinical melanoma samples, metastatic melanoma exhibited elevated FAO and tectonic family member 1 (TCTN1)." (PMID 40617808, 2025). "Mechanistically, TCTN1 enhanced FAO activity by binding to hydratase subunit A (HADHA) and subunit B (HADHB), key enzymes in the FAO pathway, thereby supporting circulating melanoma cell survival." (PMID 40617808, 2025).
oral squamous cell carcinoma (2 papers, 2023 to 2025). "TFAP2A binds to the promoters of tectonic family member 1 (TCTN1) and amyloid precursor protein (APP)to induce malignancy (proliferative, migratory and invasive capacity) in the oral squamous cell carcinoma (OSCC)." (PMID 37291585, 2023). "While the transcription factor AP2α has been reported to regulate TCTN1 expression and promote proliferation, migration, and invasion in oral squamous cell carcinoma (OSCC), our study identifies CTCF—rather than AP2α—as a key transcriptional regulator of TCTN1." (PMID 41369411, 2025).
thyroid cancer (2 papers, 2019 to 2024). "Silencing of TCTN1 was suggested to induce human thyroid cancer cell apoptosis through over-expression of cleaved caspase-3 and PARP and repression of Bcl-2." (PMID 31297133, 2019).
glioma (1 paper, 2014). A benign or malignant brain and spinal cord tumor that arises from glial cells (astrocytes, oligodendrocytes, ependymal cells). "Our immunohistochemical staining experiments showed primary expression of TCTN1 in cell nucleus through a scan of more than one hundred GBM patients, suggesting a weak link (if any) of TCTN1 and cilia in human gliomas." (PMID 25304031, 2014). "Functions and molecular mechanisms of TCTN1 in glioma warrant more investigations." (PMID 25304031, 2014). "To explore the biological significance of TCTN1 in glioma, we investigated whether it could affect cell proliferation." (PMID 25304031, 2014). "However, the function and prognostic value of TCTN1 in human glioma have never been characterized." (PMID 25304031, 2014).
tumor (7 papers, 2014 to 2025). "Studies have shown that TCTN1 is aberrantly expressed in several solid tumors, and its knockdown can induce S-phase arrest by regulating CDKs and cyclins, thereby suppressing tumor cell proliferation and migration while promoting apoptosis." (PMID 41369411, 2025). "In tumor cells, the expression of TCTN1 has been demonstrated to be overexpressed in many different cancer types." (PMID 31297133, 2019). "In addition, although TCTN1 acts as a protein scaffold that promotes tumor cell migration, its relationship with canonical cytoskeletal proteins has remained unclear." (PMID 41369411, 2025). "Mechanistically, we suggest that miR-216a-5p exerts its tumor suppressive role via targeting TCTN1." (PMID 31297133, 2019). "TCTN2, taking part to a supramolecular functional complex with TCTN1, could act in combination with it in conferring cellular phenotypes relevant for tumor growth and spread to distal sites." (PMID 29221125, 2017). "Our results demonstrate that miR-216a-5p might serve as a tumor suppressor in ESCC cells through negatively regulating TCTN1 expression, indicating the possibility that miR-216a-5p and TCTN1 might be attractive targets for ESCC therapeutic intervention." (PMID 31297133, 2019). "Given that potent regulators of developmental processes are frequently disrupted in tumorigenesis, and the primary cilium and Hedgehog pathway also play important roles in tumorigenesis, it is to be expected that TCTN1 also contributes to tumor development yet there have been no reports on it." (PMID 25304031, 2014).
cancer (5 papers, 2014 to 2025). A tumor composed of atypical neoplastic, often pleomorphic cells that invade other tissues. "Recent studies revealed that TCTN1 is widely up-regulated in various types of human cancer, and acts as an oncogene via promoting proliferation, migration, or inhibiting apoptosis." (PMID 33194647, 2020). "Concerning the role of TCTNs in cancers, available information are limited to TCTN1, which has been described as an important regulator of proliferation and migration of cancer cells." (PMID 29221125, 2017). "The only member of this family that has been reported to act as an important player in human cancers is TCTN1." (PMID 29221125, 2017). "Notably, we observed that GA (13:0)-induced G0/G1 arrest differs from the S-phase or G2/M arrest reported in cancer studies following TCTN1 knockdown, suggesting cell type-specific regulatory roles of TCTN1." (PMID 41369411, 2025). "Knock down approaches proved that TCTN1 is essential for cancer cell viability and proliferation, suggesting that its dysregulation may play a key role in tumorigenesis." (PMID 29221125, 2017). "Thus, whether TCTN1 regulate Hedgehog pathway still remains unclear, particularly in the context of human cancer biology." (PMID 25304031, 2014). "Moreover, it would be interesting to test whether, as reported for TCTN1 in GMB, TCTN2 could represent a prognostic factor for TCTN2-over-expressing cancers." (PMID 29221125, 2017). "As described for TCTN1, variation of TCTN2 expression could affect the interaction of the TCTN complex with MSK1 and influences its expression in the cilia, thereby leading to Wnt and Shh signaling transduction that can ultimately result in aberrant growth of cancer cells." (PMID 29221125, 2017). "Our analyses in these independent cohorts suggested a key role of TCTN1 gene in tumorigenesis and progression of GBM, yet there has been no direct report on its function in cancer biology." (PMID 25304031, 2014).
brain diseases (1 paper, 2021). "Three genes (AHI1, CSPP1, and TCTN1) in the top 10 of the PSGs associated with human brain diseases, with raw dN/dS > 2, are required for both cortical and cerebellar development in humans." (PMID 33441416, 2021).
infection (1 paper, 2014). The state of being infected such as from the introduction of a foreign agent such as serum, vaccine, antigenic substance or organism. "TCTN1 was stably overexpressed or silenced in U251 and U87 cells by lentiviruses infection, while the efficiency of ectopic expression of TCTN1 was validated by real-time PCR and western blot analysis." (PMID 25304031, 2014).
TCTN1 also shares sentences with these, for which no sentence is quoted: retinal degeneration (3 papers); microphthalmia (2); pancreatic cancer (2); adenomyosis (1); Meckel syndrome (1); metastatic melanoma (1); retinal diseases (1).